IL4 (interleukin 4)
Diseases named in the same sentence as IL4 in open-access papers (continued):
Sharing a sentence is not in itself a finding about the gene and the disease.
tumor (continued). "Other cytokines (CCL2, IFNγ, IL-12, IL-10, TNFα, IL-4, and IL-1β) evaluated were not significantly changed, suggesting that additional unidentified tumor-derived soluble factors promote alternative activation in BMDMs." (PMID 35008514, 2021). "One study, during proteomic analysis, found exosome having proteins like VEGF, MCP-1, IL-4, and EGF—they aid tumour cells survival, growth, and transit—those exosomes with TGF-β stimulated division of fibroblasts into myofibroblasts, supporting tumour proliferation, vascularisation, and metastasis." (PMID 34336101, 2021). "TH2-polarized CD4+ T cells secrete cytokines that can limit CTL differentiation and proliferation such as IL-10 and IL-4, while CD4+ TRegs (FOXP3+) have significant immunosuppressive functions through various mechanisms and their pro-tumor role has been described in both solid tumors and lymphomas." (PMID 33842331, 2021). "Following differentiation, TH2 cells secrete IL-4, IL-5, IL-10, IL-13, and IL-17, not all of which are beneficial in cancer and have been shown to contribute to the tumor promoting role of this subtype." (PMID 34012451, 2021). "Binding of IL-4 to IL-4 receptors on immune cells leads to STAT6 phosphorylation, nuclear translocation, and expression of GATA3 transcription factor, resulting in TH2 cytokine secretion and eventual tumor growth and metastasis." (PMID 34012451, 2021). "Mice treated with C-87 exhibited lower concentrations of the following pro-inflammatory cytokines in the tumor paw compared to vehicle-treated tumor-bearing mice: TNFα (p < 0.05), NGF (P < 0.05), IL1β (P < 0.05), IL4 (P < 0.05), IL28β (P < 0.001), IL33 (P < 0.01), MIP3α (P < 0.01)." (PMID 33469141, 2021). "Finally, the density of IL-4+ TOX+ CD4+ T cells and the levels of expression of these molecules significantly marked lesion progression from plaque to tumor." (PMID 34220814, 2021). "CAF with tumor-promoting functions secrete growth factors (HGF, IGF1, CTGF, PDGF, VEGF, LIF), cytokines (IL-1, IL-4, IL-6, IL-8, IL-10, TGF-β), and chemokines (CCL2, CCL5, CXCL5, CXCL9, CXCL10, CXCL12), WNT5α, and bone morphogenic protein 4 (BMP4), which promote tumor progression." (PMID 35008832, 2021). "Considering that IL-13 and IL-4 are primarily derived from lymphocytes, especially Th2 cells, we monitored the Th2 cell population in the lungs of MMTV-PyMT mice and detected increased infiltration of CD4+ T cells and Th2 cells along with tumor progression." (PMID 34707103, 2021). "IL-4 can promote development of specific immune cell subtypes, such as macrophages, B cells, CD4+Th2 cells, and CD8+ T cells, which play a pivotal role in the tumor progression of inflammation-related cancers, including HCC." (PMID 33906302, 2021). "Our findings are in accordance with the previous statements, as we found that both ADMSC and mature adipocytes secrete factors that could contribute to tumor development like IL6, EGF, PTGS2 and IL4 in ADMSC, and CCL5, IL1β and IGF in adipocytes." (PMID 33801973, 2021). "Moreover, a variety of tumor immune-related cytokines such as IFN-γ, TNF-α, TGF-β, IL10, and IL4 were notably increased in cells after upregulating the expression of miRNA-542-3p in HepG2 and Huh7 cells and co-cultured with T cells." (PMID 34988028, 2021). "Finally, we found that approximately half of the IL-21+CD4+ T cells in the tumor tissues were IFN-γ positive (45.6 ± 5.2%) and that IL-21+CD4+ T cells were rarely IL-4 (0.8 ± 0.3%) or IL-17 (1.6 ± 0.5%) positive." (PMID 34026621, 2021). "Because IL-4-activated macrophages cannot fully represent the characteristics of TME-educated TAMs, we further explored the in vivo roles of S100A4 in TAM alternative polarization toward a protumor phenotype using macrophages isolated from tumor grafts." (PMID 34145030, 2021). "Following differentiation, Th2 cells can produce IL-4, IL-5, IL-10, IL-13, and IL-17, not all of which are beneficial in cancer and contribute to tumor growth and metastasis." (PMID 35087869, 2021).
tumor (continued). "By using an IL-13 inhibitor (sIL-13Rα2–Fc), they found that IL-13 is essential for the tumor recurrence, while IL-4 is not." (PMID 33450900, 2021). "An additional mechanism by which tumor cells promote the TAM function is by enhancing TAM membrane cholesterol efflux through ABC transporters, which reduces lipid rafts, inhibits IFNγ-induced gene expression and favors IL-4-induced macrophage polarization." (PMID 34831183, 2021). "In addition, in H-22 tumor-bearing mice, YPF elevated the ratio of Th1/Th2 (IFN-γ/IL-4) through mature DCs, thus ameliorating Th2-biased immune state." (PMID 34722304, 2021). "Importantly, miR-195-5p has been reported to play an essential role in regulating NOTCH2-mediated tumor cell EMT, thereby affecting IL-4-related M2-like TAM polarization in CRC." (PMID 34277412, 2021). "The increased IFNG response together with IL4, IL10, VEGF, TGF-beta and immune checkpoints comprise the tumor microenvironment that dominating the immune response, making artificial manipulation of one component only transiently alter the equilibrium reached by such biological response network." (PMID 34566988, 2021). "Subsequently, the tumor cell microenvironment was filled with abundant growth factors and inflammatory mediators [colony stimulating factor-1 (CSF-1), IL-4, IL-10, and TGF-β], which changed the phenotype of macrophages into M2-type macrophages with the function of promoting tumor growth." (PMID 34950700, 2021). "In blood and tumors of subcutaneously transplanted tumor mice and CAC mice, the Th1/Th2 ratio (shown by IFN-γ/IL-4) was decreased after romidepsin treatment, which could be reversed when combined with anti-PD-1 treatment." (PMID 32632663, 2021). "Altogether, ILC cells including NK cells could contribute to the increased level of TNF-alpha, GM-CSF, IFN-gamma, IL-4, IL-5, IL-13, IL-17, and IL-22, modulating TME and contributing to tumor progression or antitumor activities." (PMID 35008550, 2021). "Irrespective of their original functions IL-4 and IL-13 cytokines are capable of promoting tumor cell growth via autocrine and paracrine mechanisms, while inhibiting attacking immune cells at the same time." (PMID 33804263, 2021). "Over-expression of IL-12 could inhibit IL-4 and STAT6 in human CC stem cells and inhibit the survival of CC stem cells in vitro and their tumor formation ability in mice." (PMID 33450900, 2021). "NK-92/5.28.z cells secreted high amounts of effector molecules such as granzymes, granulysin, and perforin upon interaction with RMS tumor cells, while the levels of secreted cytokines such as TNF-α, IL-2, IL-6, and IL-4 were minimal or below the detection limit." (PMID 33809981, 2021). "The data herein suggest that their expression alone does not blunt the development of CRC, indicating that the reduction in average tumor size seen in M(IL4)-treated mice is likely not dependent on arginase-1, FIZZ1 or Ym1." (PMID 34691050, 2021). "This study examined the use of a DCV that was generated with IL-4, GM-CSF, and pulsed together with autologous tumor lysate with or without OK-432 (agent derived from killed Streptococcus pyogenes)." (PMID 34572775, 2021). "As well, we did not observe any difference in the ratio of IFN-γ to IL-4 production in the 4T1-PIP and 4T1-EV tumor cells as assessed by enzyme-linked immunosorbent assay, ELISA." (PMID 33777801, 2021). "In LLC xenograft mice, endostatin inhibited tumor angiogenesis by reducing the number of CD31+ cells and VEGF expression, aggravated hypoxia, and increased levels of inflammatory cytokines (IL-4, IL-6, IL-10) in tumor and CCL2 expression in endothelial cells and fibroblasts." (PMID 34209679, 2021). "Increased secretion of IL-6, TNFα, CCL2, CCL5, CXCL9 and GM-CSF, which are pro-inflammatory factors combined with decreased secretion of anti-inflammatory factors including IL-4, IL-28A, CCL24, CXCL12 and SCF from infected HEL299 fibroblasts, is expected to be tumor-promoting and enhance metastasis." (PMID 34575976, 2021).
tumor (continued). "The source of IL-4 and IFN-γ could be tumor cells, the tumor-infiltrating lymphocytes, mesenchymal cells or macrophages." (PMID 34925244, 2021). "Through the production of inhibitory cytokines such as IL-4, IL-10, and transforming growth factor (TGF)-β, they suppress the immune response, encourage tumor invasion, development and infiltration, enhance angiogenesis, and prevent T cells from having an effective anti-tumor impact." (PMID 34368156, 2021). "Moreover, it was demonstrated that IL-4 increased production of reactive oxygen species (ROS) in CRC, contributed to tumor mediated inflammation and tumor progression." (PMID 35008550, 2021). "When stimulated by Th2 cytokines, including M-CSF, GM-CSF, IL-4, IL-10, and TGF-β, macrophages differentiate into the M2 phenotype, which is equipped with the functions of immune suppression, facilitating tumour progression, cell proliferation and angiogenesis." (PMID 34930387, 2021). "In contrast, control tumor lysates-treated DCs increased the frequency of Th2 (CD4+IL-4+), CD4, and CD8 regulatory T cell subtypes, none of which was observed with DCs loaded with PAM-lysates." (PMID 33915703, 2021). "And tumor infiltrating Bcl6–/– Treg cells exhibited markedly decreased expression of Foxp3, while upregulating the expression of TFs and cytokines related to other lineages, including Tbet, RORγt, GATA3, IL4, and IL17, suggesting a weakened lineage stability." (PMID 32477338, 2020). "Moreover, widespread cell death triggers efferocytosis-induced wound-healing cytokines, such as IL-4, IL-10, IL-13, and transforming growth factor β (TGF-β), in the TME to further promote metastatic tumor progression." (PMID 32346605, 2020). "In ESCC and CRC, in turn, the more advanced and aggressive disease, the less IL-4 protein and mRNA are present and the alterations occur in non-cancerous adjacent tissue rather than in tumor." (PMID 32512917, 2020). "However, there were significant differences between cancer types in IL-4 protein and IL4 and IL4Ra transcript numbers, in both tumor and adjacent tissue, when they were analyzed directly and not as a fold-change." (PMID 32512917, 2020). "In DC/CIK therapy, the DCs are derived from mononuclear cells obtained by leukapheresis in typical GM-CSF/IL-4-supplemented medium and loaded with antigens (autologous tumor lysate or peptides)." (PMID 33679709, 2020). "Similarly, PD-L2 can be induced by the adaptive immune resistance mechanism, depending on the milieu of inflammatory cytokines in the tumor microenvironment; for example, IFN-γ, IL-4 and colony-stimulating factor 2 (CSF-2) upregulate PD-L211." (PMID 33339860, 2020). "For example, cytokines IL-4 and IL-10 secreted by tumor cells or T cells can polarize macrophages to their M2 state in which they are capable of secreting TGF-B1 and CXCL12 to inhibit CD8+ T cell function in support of tumor cell survival and metastasis." (PMID 31979136, 2020). "Furthermore, the cytokines related to tumor growth, EMT, metastasis and drug resistance, such as IL-1B, IL-2, Il-4, IL-6, IL-10, IL-17, KC (GRO), were mainly expressed in mT obese models." (PMID 32411709, 2020). "In addition, the expression of several cytokines, including interferon-γ (IFN-γ), tumor necrosis factor-α (TNF-α), interleukin-4 (IL-4), and IL-10, had been determined in the IDO shRNA-treated LLC1-tumor bearing mice in our previous study." (PMID 32933162, 2020). "Suppressive immune cells in the TME often preferably express pro-tumor Th2 secreted cytokines, such as IL-4 and IL-13, rather than anti-tumor Th1 (e.g., IL-2 production), or secreted cytokines like IFN-γ and tumor necrosis factor-β (TNF-β)." (PMID 32843053, 2020). "Considering that tumor cells that have undergone EMT are more likely to metastasize, we next sought to measure the migratory properties of the immortalized MCF10A cells exposed to M0 and M(IL‐4 + IL‐13) THP‐1 CM." (PMID 32713010, 2020).
tumor (continued). "Kang revealed that CXCL9, CXCL10, IL-4, CXCL1, and CXCL13 expression may be related to tumor regression in mice with T. spiralis infection." (PMID 32692308, 2020). "IL-4 and IFN-γ levels correlate with tumor and T cell dynamics." (PMID 33362239, 2020). "Th2 cytokines such as IL-4, IL-10, IL-13, and Tgf-β that inhibit anti-tumor responses can also be released by myeloid derived suppressor cells (MDSC) that have been activated by tumor cells." (PMID 32508830, 2020). "IL-4 and IFN-γ concentrations mirror tumor cell and active T cell dynamics, respectively." (PMID 33362239, 2020). "In line with declining IL-4 concentration along with increasing cancer aggressiveness in ESCC and CRC, IL4 expression was lower in ESCC cancers metastasizing to lymph nodes and tended to be inversely correlated with primary tumor extension in CRC." (PMID 32512917, 2020). "The cells of tumor and TME secrete CCL2 and macrophage colony-stimulating factor (M-CSF) and attract a large number of inflammatory monocytes to tumor sites where they differentiate into TAMs due to secretion of IL4, IL10, and IL13." (PMID 32582698, 2020). "In order to characterize the M-406/CBi/L model with respect to cytokines involved in the different phases of tumor immunoediting, it was evaluated the concentration of Th-1 (IFN-γ, IL-2) and Th-2 (IL-10, IL-4) cytokines in serum from tumor bearing animals during EL, EQ and ES phases." (PMID 33312693, 2020). "Therefore, we determined tumor cytokine expression of type 1 (TNF-α and IFN-γ), type 2 (IL-4 and IL-5), and regulatory (IL-10) cytokines." (PMID 32547942, 2020). "The differences in IL4 and IL4Ra transcripts between adjacent and tumor tissue were non-significant." (PMID 32512917, 2020). "Others have described modulation of cytokine production of IL-1α, IL-1β, IL-2, IL-4, IL-6, IL-8, IL-10, IL-17A, TNF-α, and IFN-γ on tumor cells treated with conventional PDT, but their increase or decrease seems to highly depend on the cell line and PDT protocol used." (PMID 32326519, 2020). "In turn, there was an inverse correlation between IL-4 protein concentration and expression of IL4 transcripts in tumor (r = −0.40, p = 0.019) and tumor-adjacent tissue (r = −0.43, p = 0.011) as well as between their fold-change (tumor-to-adjacent; r = −0.42, p = 0.015)." (PMID 32512917, 2020). "Thus, a CBi/L mouse with a tumor in EQ phase and high levels of IFN-γ and IL-4 will be prone to resume growth and eventually enter into the ES phase." (PMID 33312693, 2020). "The strategy of using dendrimers rich in mannose was not useful for specific target of macrophages treated with IL-4 in the tumor microenvironment." (PMID 33048944, 2020). "In addition, tumor microenvironment (TME), like IL4, IL-6, IL-10, TGF-β, paralyzing the immune responses." (PMID 33233552, 2020). "One of such immune subsets is the tumor-associated macrophages (TAMs) which are polarized into M2 macrophage phenotype by IL-10, TGF-β, IL-4, or IL-13 present in the TME, and drive tumor progression by supporting angiogenesis and recruitment of CD4+FoxP3+ T regulatory cells (Tregs)." (PMID 33117354, 2020). "The steroidogenesis-inducing type-2 cytokines such as IL4 are also often present in the TME31,32, thus we next sought to examine the steroidogenic capacity (i.e. Cyp11a1 induction) of T cells infiltrating tumors, and their impact on tumor development." (PMID 32680985, 2020). "As with other treatments, IL-4 and IFN-γ levels follow tumor and T cell dynamics." (PMID 33362239, 2020). "Furthermore, the correlation of acupuncture and moxibustion with T-bet/IFN-γ, GATA3/IL4, inflammation markers IL-6 and C-reactive protein (CRP), and tumor marker Ca199 was evaluated." (PMID 33144870, 2020). "IL-4 and IFN-γ dynamics follow tumor cells and T cells, respectively." (PMID 33362239, 2020).
tumor (continued). "Similarly, the MOv18 mouse/rat surrogate IgE (engineered for in vivo studies, as described in more detail below), mediated tumour cell ADCC by rat primary monocytes and U937 cells, and ADCP by IL-4-primed U937 cells with upregulated CD23 expression." (PMID 33081206, 2020). "Likewise, cytokines such as IL-1β, IL-4, IL-13 and TNF-α facilitate the cell fusion process that results in increased tumour-hybrid formation." (PMID 31266502, 2019). "Tumor-conditioned media (TCM) only, cytokine only (IL-4, IL-10, and M-CSF), TCM with IL-4 and IL-10, TCM with IL-4 and M-CSF, TCM with IL-10 and M-CSF, and TCM with IL-4, IL-10, and M-CSF (the last condition being the in vitro TAM generation method)." (PMID 31138333, 2019). "Frequently TAMS and TANS are polarized towards a pro-tumor phenotype, M2 and N2, and in combination with Tregs produce immunosuppressive cytokines/ligands including transforming growth factor β (TGF-β), IL-4, arginase, reactive oxygen species, and programmed death ligand-1 (PD-L1)." (PMID 30736355, 2019). "After differentiation into immature DCs using IL-4 and GM-CSF, the cells were pulsed with or without 100 μg/mL tumour-specific lysate for 6 h at 37 °C." (PMID 30283982, 2019). "In contrast to the coculture with tumor cells, neither MΦ-polarizing stimuli such as 100 ng/mL LPS (lipopolysaccharide) + 100 U/mL interferon-γ (IFNγ), 20 ng/mL interleukin-4 (IL-4), nor the resolution-phase stimulus resolvin D1 increased miR-375 levels in MΦ." (PMID 30850595, 2019). "We found that in mice with hetero and homozygous deletion of Dll1 in DCs, the numbers of IFN-γ-producing MUT1-specific lymphocytes were markedly decreased in the tumor, whereas the numbers of tumor-infiltrating IL-4-producing cells were not altered." (PMID 30940183, 2019). "Meanwhile, tumor immune-related pathways were also enriched, such as B cell development pathway, cd28 signaling in T Helper cell, chemokine signaling, IL-1 signaling, IL15 signaling, IL-2 signaling, IL-3 signaling, IL-4 signaling, and IL-8 signaling." (PMID 31258820, 2019). "IL-4 produced by CD4+ T cells may inhibit angiogenesis, promote the infiltration of eosinophils and macrophages into tumour and exert anti-tumour effects, while IL-5 mainly has immunosuppressive and tumour-promoting function." (PMID 31519961, 2019). "Furthermore, HH/GLI signaling is able to polarize Th2 differentiation of T-cells by inducing interleukin-4 (IL4) production, thereby promoting allergic responses and reducing cytotoxic T-cell function in the context of tumor immunity." (PMID 31878932, 2019). "Ex-vivo stimulation of tumor-infiltrating CD4+ and CD8+ memory T-cells (PMA/Ionomycin) revealed a prominent shift from a Th2 towards a Th1 phenotype with an increased intracellular ratio of IFN-γ to IL-4." (PMID 30506500, 2019). "In addition, several cytokines, such as IL-4, IL-13, RANKL, and TNF-α, seem to play an important role in the process of macrophage fusion, myoblast fusion and even in tumour-hybrid formation." (PMID 31266502, 2019). "IL4 and IL13 can activate MDSCs to exert immunosuppression leading to promote tumor growth." (PMID 31540495, 2019). "4/21 ICR expressing CAR-T cells achieved enhanced resistance to IL-4, exhibiting the comparable, if not improved, anti-tumor activities to the 4/7 ICR-CAR T cells in vivo." (PMID 31379876, 2019). "In this study, an in vitro method to generate monocyte- derived TAM using tumor- conditioned media (TCM) and a cytokine cocktail containing IL-4, IL-10, and M-CSF was utilized to study the phenotype, morphology, and function of TAM across multiple cancer types." (PMID 31138333, 2019). "Suppression of IL4 and IL13 as well as IL4Rα and IL13Rα1 might be tumor-suppressive especially in poor prognostic group of cancers expressing both IL4Rα and IL13Rα1 as like IL4Rα+IL13Rα1+ subgroup of CCRCC." (PMID 31540495, 2019).